EPSTI1 (epithelial stromal interaction 1)
Diseases named in the same sentence as EPSTI1 in open-access papers (continued):
Sharing a sentence is not in itself a finding about the gene and the disease.
cancer (15 papers, 2012 to 2024). A tumor composed of atypical neoplastic, often pleomorphic cells that invade other tissues. "The host gene, EPSTI1, encodes the epithelial–stromal interaction 1 protein, which has been studied for its role in cancer." (PMID 36287121, 2022). "Depleting KSR1 caused cancer cells to generate less EPSTI1 and to share more features with healthy cells, such as higher levels of E-cadherin on their surface and reduced mobility." (PMID 33970103, 2021). "Moreover, the EMT-inhibiting EHF and TP63 were down-regulated and the cancer invasion-associated EPSTI1 was up-regulated implying that proliferation of mesenchymal elements and may be important in the epithelial plasticity and cancer progression." (PMID 25706888, 2015). "In the current study, we demonstrate the crucial role of Epsti1 in muscle regeneration and prevention of muscle wasting from cancer cachexia." (PMID 38993551, 2024). "Epithelial–stromal interaction 1 (EPSTI1) is a gene that responds to interferons and is well known for its role in the metastasis of malignant tumours." (PMID 36567857, 2022). "CircEPSTI1 is derived from the EPSTI1 gene, which is characterized by its participation in extensive epithelial-stromal interactions, innate immunity, and cancer invasion and metastasis." (PMID 32826876, 2020). "Considering the potential significance in macrophages and DCs, EPSTI1 deserves more in-depth research and might be another target for cancer immunotherapy." (PMID 36330510, 2022). "Adding EPSTI1 to the cancer cells that lacked KSR1 restored the traits associated with metastasis, such as high levels of N-cadherin, and allowed the cells to move more easily." (PMID 33970103, 2021). "Researchers have revealed that the high abnormal expression of EPSTI1 may have a very important role in the invasion and invasion of cancer." (PMID 33534779, 2021). "EPSTI1 has been reported overexpressed in multiple cancers and involved in cancer progression." (PMID 30887698, 2019). "Moreover, the EPSTI1 gene may play a potential regulatory role in the body’s natural immunity, being shown to promote tumor invasion and metastasis in various cancer types." (PMID 36421816, 2022). "In a comparison to AXL with an established role in enhancing resistance to ICB, CYTH4, DENND1C, AOAH, EPSTI1, and TBC1D10C display a stronger correlation with immune checkpoints in human cancers." (PMID 36588164, 2023). "CYTH4, AOAH, DENND1C, TBC1D10C, EPSTI1, SERPINB8, and GIMAP7 are novel and robust individual genes in predicting resistance to ICB in multiple cancer types." (PMID 36588164, 2023). "In line with the notion, mice lacking Epsti1 exhibit exacerbated muscle atrophy accompanied by increased inflammatory response in cancer cachexia model." (PMID 38993551, 2024). "Additionally, CYTH4, DENND1C, AOAH, EPSTI1, and TBC1D10C exhibit strong correlations with a set of immune checkpoints not only in SKCM but also across a spectrum of human cancers." (PMID 36588164, 2023). "Interestingly, we found downregulation of several components (integrins α1/α5/α6, epithelial-stromal interaction 1 (EPSTI1), fibronectin type III) that may, together with altered MUC4 expression in cancer cells, modify epithelial-stromal interactions." (PMID 22393391, 2012).
tumor (15 papers, 2007 to 2025). "TIDE found significantly lower infiltration abundance of M2 tumor-associated macrophages (TAM) in the high EPSTI1 group in both cohorts when assessing immunosuppressive cells (P < 0.05)." (PMID 36330510, 2022). "Determining how KSR1- and ERK-dependent signaling promotes EPSTI1 translation should yield novel mechanisms underlying tumor cell metastatic behavior." (PMID 33970103, 2021). "Expression levels of EPSTI1 associate with tumor initiation, stem cell–like properties, and EMT." (PMID 30572883, 2018). "To further investigate the relationship between EPSTI1 and tumor immune cells, we analyzed 32 stage III CC patients from the single-cell dataset GSE178341." (PMID 36330510, 2022). "Upon removal of KSR1 or EPSTI1, the tumor cells switch back from highly migratory and invasive EMT-like state to the epithelial state." (PMID 33970103, 2021). "However, Epsti1 KO cachectic mice exhibited declines in tumor-free body weights and the weights of TA and GA muscles compared to those of WT cachectic mice." (PMID 38993551, 2024). "Many downregulated genes in tumour‐infiltrating peripheral CD8+ T cells are associated with classical IFN responses (IFI6, IFI27, MX1, STAT1, EPSTI1 PARP9, ISG15), cell proliferation (STMN1, CENPF, HELLS, NUSAP1, and DNPH1), and T cell costimulation (CD28, TMIGD2, TNFRSF4, CD27, and TNFRSF18)." (PMID 39350478, 2024). "The CREBBP-regulated gene, EPSTI1, is known to promote tumor invasion and metastasis." (PMID 31025158, 2019). "For instance, indicators associated with the IFN pathway, such as the characteristics of interferon-stimulated genes (ISGs) including MX1, EPSTI1, XAF1, and GBP1, have been correlated with tumor sensitivity to VSV." (PMID 40698086, 2025). "Further characterization of KSR1, EPSTI1 and the additional effectors repurposed by dysregulated translation in CRC should reveal additional novel mechanisms critical to CRC tumor survival and progression." (PMID 33970103, 2021). "Another study suggested the interaction of EPSTI1 with valosin-containing protein (VCP) and the subsequent activation of NF-κB signaling contributed to the increased tumor invasion and metastasis." (PMID 33970103, 2021). "Five genes (62.5%) demonstrated tumour acquired methylation (EMILIN2, SALL1, DBC1, FBLN2 and CIDE-A), whilst the remaining 3 (COMP, EPSTI1, SIM2) showed equal methylation in the corresponding normal breast tissue DNA." (PMID 20205715, 2010). "We analyzed the role of ICDRs in tumor immune microenvironment by using the previous data of single cell transcriptome, and we analyzed the distribution of several key genes (PSME2, TYMP, KLHDC7B, GBP5, EPSTI1, STAT1 and OAS2) in different cell types." (PMID 40259929, 2025).
infection (7 papers, 2020 to 2025). The state of being infected such as from the introduction of a foreign agent such as serum, vaccine, antigenic substance or organism. "EPSTI1, NACAP1, SHROOM3, C19ORF35, and MX1 as the essential features play important roles in the infection and immune response to novel coronavirus." (PMID 35620480, 2022).
EPSTI1 also shares sentences with these, for which no sentence is quoted: oral squamous cell carcinoma (2 papers); ZIKV infection (2); dyslipidaemia (1); endothelial dysfunction (1); invasive breast carcinoma (1); lung squamous cell carcinoma (1); lymphadenitis (1); pancreatic cancer (1); pancreatic ductal adenocarcinoma (1); polymyositis (1); rheumatoid arthritis (1).